FAH (fumarylacetoacetate hydrolase)
Tractability: PROTAC: ubiquitination databases record sites on it; its protein half-life has been measured.
Target class: Enzyme; Hydrolase
Gene: Protein-coding gene on chromosome 15 (80,152,292 to 80,186,990, forward strand). Ensembl gene ENSG00000103876.
Subcellular location (Human Protein Atlas): Cytosol; Nucleoplasm
Pathways (Reactome):
Metabolism: Tyrosine catabolism
Gene Ontology:
Molecular function: protein binding; fumarylacetoacetase activity; catalytic activity
Biological process: L-phenylalanine catabolic process; L-tyrosine catabolic process; aromatic amino acid metabolic process
Cellular component: extracellular exosome; cytosol
Genetic constraint (gnomAD): Loss-of-function variants: 42 observed, 50.9 expected, observed/expected ratio (o/e) 0.83, 90% interval 0.64 to 1.07. The upper end of that interval is the gene's LOEUF score, 1.07, which puts it in group 4 of 6, group 1 being the genes least tolerant of losing a copy. Missense variants: 482 observed, 553.84 expected, observed/expected ratio (o/e) 0.87, 90% interval 0.81 to 0.94. Synonymous variants: 195 observed, 209.76 expected, observed/expected ratio (o/e) 0.93, 90% interval 0.83 to 1.05.
Gene-disease validity (ClinGen):
ClinGen rates the evidence that FAH causes each of these diseases.
tyrosinemia type I (autosomal recessive): Definitive.
Homologues: Orthologues: macaque FAH (97% identical), chimpanzee FAH (94% identical), pig FAH (92% identical), mouse Fah (89% identical), rat Fah (89% identical), dog FAH (86% identical), guinea pig FAH (85% identical), tropical clawed frog fah (76% identical), rabbit FAH (68% identical), Caenorhabditis elegans fah-1 (64% identical), zebrafish fah (63% identical), Drosophila melanogaster Faa (60% identical). Paralogues in human: FAHD2A (20% identical), FAHD2B (19% identical), FAHD1 (15% identical).
Diseases named in the same sentence as FAH in open-access papers:
FAH is named in the same sentence as 70 diseases in open-access papers, as found by Europe PMC text mining. Sharing a sentence is not in itself a finding about the gene and the disease. The quoted sentences say what the papers report.
Tyrosinemia type 1 (51 papers, 2005 to 2026). "For example, identifying a pathogenic variant in FAH (fumarylacetoacetate hydrolase) can prompt early initiation of nitisinone therapy in tyrosinemia type 1, preventing hepatic and renal complications." (PMID 41404425, 2025). "CRISPR-Cas9 can be employed to correct the genetic mutation responsible for the enzyme deficiency in conditions such as hereditary tyrosinemia type 1, where a deficiency in fumarylacetoacetate hydrolase [FAH] leads to toxic metabolite accumulation." (PMID 38999541, 2024). "Several loss-of-function mutations in FAH are associated with hereditary tyrosinemia type I in humans, characterized by elevated blood tyrosine levels." (PMID 38870230, 2024). "Another curious example comes from the work of Scalet and colleagues that studied the splicing mutation c.1062+5G>A in the FAH gene, which causes Tyrosinemia type 1." (PMID 37834063, 2023). "Tyrosinemia type 1 (OMIM #276700) is a rare metabolic disorder caused by a defect of fumarylacetoacetate hydrolase (encoded by FAH gene)." (PMID 37065762, 2023). "The buildup of cytotoxic metabolites and liver cell death is due to type I tyrosinemia disease caused by a deficiency in the fumarylacetoacetate hydrolase (FAH) enzyme." (PMID 36429042, 2022). "Tyrosinemia type I (HT1) is a rare autosomal recessive genetic disease caused by a deficiency in fumarylacetoacetate hydrolase (FAH, EC 3.7.1.2), the last enzyme in the tyrosine catabolism pathway." (PMID 33670179, 2021). "Tyrosinemia type I is attributed to a mutation in the fumarylacetoacetate hydrolase gene (Fah-/-), and it is known that a loss/mutation in the homogentisic acid dioxygenase (Hgd) gene located on chromosome 16 is protective against this disease." (PMID 32155721, 2020). "More than 100 mutations in the gene encoding fumarylacetoacetate hydrolase (FAH) cause hereditary tyrosinemia type I (HT1), a metabolic disorder characterized by elevated blood levels of tyrosine." (PMID 31300554, 2019). "CRISPR/Cas9 technique already can efficiently relieve disease phenotypes of hereditary tyrosinemia type I (HT-1) in mice by correcting fumarylacetoacetate hydrolase (FAH) mutation (causing HT-1)." (PMID 30915036, 2019). "Tyrosinemia type 1 is an autosomal recessive condition caused by a deficiency of fumarylacetoacetate hydrolase (FAH)." (PMID 31240158, 2019). "We observed overexpression of succinylacetone (4,6-dioxoheptanoic acid), a tyrosine metabolite which typically accumulates in patients with tyrosinemia type 1 who have recessive mutations in the hepatic enzyme fumarylacetoacetate hydrolase (FAH)." (PMID 29503615, 2018). "Fumarylacetoacetate hydrolase deficiency, results in type 1 tyrosinemia with hepatorenal involvement, and a high level of succinylacetone in blood plasma and urine." (PMID 27500280, 2016). "Recently, a mouse model of hereditary tyrosinemia type I(HT1)caused by a point mutation of fumarylacetoacetate hydrolase (FAH) was phenotypically restored via Cas9‐mediated gene repair in vivo." (PMID 26964564, 2016). "Tyrosinemia type 1 (TT1) is an autosomal recessive disorder caused by deficiency of the enzyme fumarylacetoacetate hydrolase (FAH)." (PMID 24016420, 2013). "Tyrosinemia type 1(TT1) is an autosomal recessive disorder caused by deficiency of the enzyme fumarylacetoacetate hydrolase (FAH), which catabolizes fumyralacetoacetate into fumarate and acetoacetate." (PMID 24016420, 2013). "The most promising study to date demonstrates liver disease reversal following transplantation of enriched HSCs into fumarylacetoacetate hydrolase- (FAH-) deficient mice, an animal model of tyrosinemia type I." (PMID 22121493, 2012). "Tyrosinemia type I results from the deficiency of the enzyme fumarylacetoacetate hydrolase (FAH) (EC 3.7.1.2) which is encoded by FAH gene." (PMID 23193487, 2012). "They used a mouse model of inherited tyrosinemia type I which carries a single point mutation rendering it deficient in fumarylacetoacetate hydrolase (FAH)." (PMID 21774770, 2011).
Tyrosinemia type 1 (continued). "4-hydroxyphenylpyruvate dioxygenase activity in liver was normal, which is atypical for tyrosinemia type I. A novel mutation was found in the FAH gene: c.103G>A (Ala35Thr)." (PMID 20003495, 2009). "A deficiency in FAH causes hereditary tyrosinemia type I (HTI; OMIM 276700), the most severe disease of the pathway." (PMID 15638932, 2005). "Del100 and del231 were originally identified while studying the impact of NMD on hereditary tyrosinemia type I. During the characterization of the effects of the W262X mutation on FAH mRNA metabolism, we detected two minor alternative transcripts." (PMID 15638932, 2005). "Whole exome sequencing identified FAH gene mutation consistent with tyrosinemia type 1." (PMID 39050308, 2024). "A deficiency in human FAH leads to hereditary tyrosinemia type I (HT1), an autosomal recessive disorder that results in the accumulation of toxic metabolites such as succinylacetone, maleylacetoacetate, and fumarylacetoacetate in the liver and kidney, among other tissues." (PMID 33670179, 2021). "Further, deficiency of fumarylacetoacetate hydrolase (tyrosinemia type 1) could be associated with secondary hypermethioninemia due to the associated liver damage and/or accumulation of fumarylacetoacetate, thus inhibiting MAT." (PMID 34449519, 2021). "As the human FAH gene contains 14 exons and is 35 kb long, a single zinc finger–based homologous recombination approach cannot be used to correct the different mutations in newborns with tyrosinemia type I, unless new targeting strategies are designed for each new mutation." (PMID 21765802, 2011). "Tyrosinemia type 1 (HT1), due to deficient activity of fumarylacetoacetate hydrolase, causes accumulation of succinylacetone (SA)." (PMID 41767123, 2026). "For further diagnostic work-up, a virtual panel from exome sequencing focusing on the genes FAH (Tyrosinemia type I, MIM #276700) and GSTZ1 (Maleylaceoacetate Isomerase Deficiency, MIM #617596) was performed in leucocyte-derived DNA of the index." (PMID 38535121, 2024). "Tyrosinemia type 1 (TT1, OMIM#276700) is a rare inborn metabolic disease, caused by a deficiency of the fumarylacetoacetate hydrolase (FAH) enzyme, which disrupts the catabolic pathway of tyrosine (Tyr)." (PMID 39728402, 2024). "Transplantation of HSPCs into fumarylacetoacetate hydrolase (Fah)-deficient mice showed that they could transdifferentiate into functional hepatocytes, leading to the regeneration of the injured liver, thus correcting the phenotype in a mouse model of human tyrosinemia type I." (PMID 37681858, 2023). "Tyrosinemia Type 1 (TT1; McKusick 27670) is an inborn error of tyrosine metabolism caused by a deficiency of the enzyme fumarylacetoacetate hydrolase (FAH)." (PMID 31623189, 2019). "Tyrosinemia type I (MIM# 276700; TYRSN1, TYR I) is an inborn error of tyrosine metabolism caused by pathogenic variants in fumarylacetoacetate hydrolase (FAH; MIM# 613871, EC 3.7.1.2), the final enzyme in the tyrosine degradation cascade [Grompe, 2001]." (PMID 27397503, 2016). "Tyrosinemia type I (TYRSN1, TYR I) is caused by fumarylacetoacetate hydrolase (FAH) deficiency and affects approximately one in 100,000 individuals worldwide." (PMID 27397503, 2016). "A novel missense point mutation that probably creates a donor splice site in the exon 8 of FAH gene for tyrosinemia type I has also been identified." (PMID 23193487, 2012). "In type I tyrosinemia patients with a cirrhotic liver, liver nodules demonstrating a reversion to the normal FAH genotype and showing normal FAH enzyme activity have been described." (PMID 20003495, 2009). "Type 1 Tyrosinemia (HT1) is a rare genetic disorder stemming from mutations in the tyrosine catabolism enzyme fumarylacetoacetate hydrolase (FAH), for which there exists no available cure." (PMID 35668715, 2022).
Tyrosinemia type 1 (continued). "Tyrosinemia type 1 (TYR1, OMIM 276700) is a rare autosomal recessive disorder of amino acid metabolism that is caused by a defect in the final enzyme of the pathway of tyrosine degradation, namely fumarylacetoacetate hydrolase (FAH)." (PMID 28893311, 2017). "Carrier of tyrosinemia type I was diagnosed by sequencing FAH (fumarylacetoacetate hydrolase) gene." (PMID 23193487, 2012). "Although, in the present study, there were no participants with congenital type 1 tyrosinemia caused by FAH gene abnormality, not only succinylacetone but also tyrosine and phenylalanine levels showed significant elevated levels in the LC group compared to the control group." (PMID 31803070, 2019). "Depletion of fumarylacetoacetate hydrolase (FAH), an enzyme that catalyzes the last step of tyrosine metabolism, led to a hereditary tyrosinemia type I (HT1)." (PMID 35255981, 2022). "The etiology of hereditary tyrosinemia type 1 (HT-1) is the absence of fumarylacetoacetate hydrolase (FAH), an enzyme that catalyzes the last stage of the tyrosine breakdown process." (PMID 39050308, 2024). "We hereby present, a nonconsanguineous family with index case confirmed as tyrosinemia type 1 by urine organic acid study and sequencing of FAH gene in the parents followed by prenatal diagnosis in subsequent pregnancy." (PMID 23193487, 2012). "Dysfunction of metabolic enzymes, fumarylacetoacetate hydrolase (FAH), tyrosine aminotransferase (TAT), and 4-hydroxyphenylpyruvic acid dioxygenase (HPD) in the phenylalanine and tyrosine catabolic pathway results in tyrosinemia type I, II, and III, respectively." (PMID 31537781, 2019).
tyrosinemia (25 papers, 2009 to 2026). An autosomal recessive inherited metabolic disorder caused by mutations in the FAH, HPD, and TAT genes. "Mutations in the FAH gene that lead to the abolishment of enzyme activity in humans can result in a condition called tyrosinemia." (PMID 40429777, 2025). "The Fah knockout mouse carries a deficiency of fumarylacetoacetate hydrolase (FAH) resulting in tyrosinemia." (PMID 36965009, 2023). "They studied the correction by prime editing of a G > A point mutation (position +10 in their pegRNA) in the FAH gene in chemically derived hepatic progenitors (CdHs) from a mouse model of hereditary tyrosinemia (HT1 mice)." (PMID 36831203, 2023). "They tested their method to remove a 1.38 kb pathogenic insertion in the FAH gene in a mouse model of tyrosinemia and replace it with a 19 bp sequence." (PMID 36831203, 2023). "Type I tyrosinemia involves the loss of fumarylacetoacetate hydrolase (FAH), which converts fumarylacetoacetate to fumarate and acetoacetate a few steps further downstream of the tyrosine degradation pathway." (PMID 35736461, 2022). "In 2016, a study on human hereditary tyrosinemia (HHT) showed slightly promising results on correcting the fumarylacetoacetate hydrolase (FAH) mutation." (PMID 35214191, 2022). "Various DNA-editing approaches have been implemented for the treatment of type I hereditary tyrosinemia, which is attributed to loss of function of fumarylacetoacetate hydrolase (FAH)." (PMID 36032737, 2022). "Tyrosinemia is a rare metabolic disease showing autosomal recessive inheritance associated with a deficiency of the enzyme fumarylacetoacetate hydrolase." (PMID 31501693, 2019). "CRISPR/Cas9 was used in an experiment to correct the FAH mutation in liver cells in a mouse model of the human genetic disease tyrosinemia." (PMID 29592810, 2018). "Deficiency of fumaryl acetoacetate hydrolase (encoded by FAH; the enzyme is required in tyrosine catabolism) causes a buildup of fatty acids and toxic metabolites that result in liver failure, known as tyrosinemia." (PMID 26755558, 2016). "Type I hereditary tyrosinemia is a metabolic disorder caused by defective production of fumarylacetoacetate hydrolase (FAH), which catalyzes the final step in hepatic tyrosine catabolism." (PMID 27105497, 2016). "Type I tyrosinemia is caused by a mutation in the gene encoding for the fumarylacetoacetate hydrolase or fumarylacetoacetase (FAH) enzyme, an enzyme in the tyrosine degradation pathway." (PMID 20003495, 2009). "In conclusion, we present a patient homozygous for a previously undescribed mutation in the FAH gene (Ala35Thr), leading to a mild type I tyrosinemia and probably amenable with diet." (PMID 20003495, 2009). "For this, we envision that, after obtaining appropriate IRB approval, human embryonal, fetal or neonatal hepatocytes would first be propagated in immuno-deficient mice that lack the enzyme fumarylacetoacetate hydrolase (Fah), and that serve as a model for type 1 hereditary tyrosinemia." (PMID 41440033, 2025). "Tyrosinemia is a genetic disease caused by a mutation in the FAH gene in humans." (PMID 29592810, 2018). "A deficiency of FAH is associated with type 1 hereditary tyrosinemia." (PMID 27469031, 2016). "The diagnosis of type I tyrosinemia is supported by the demonstration of 4-oxo-6-hydroxyheptanoic acid in urine, a strongly decreased but measurable FAH enzyme activity in liver tissue and fibroblasts and the demonstration of a novel mutation in the FAH gene (Ala35Thr)." (PMID 20003495, 2009). "Tyrosinemia is featured by elevated tyrosine and its derivatives in serum and urine due to defected enzymes in tyrosine-catabolic pathway, such as FAH, TAT, and HPD20." (PMID 31537781, 2019). "Conversely, deletion of the genes encoding enzymes that function upstream of FAH (e.g., homogentisic acid dioxygenase [HGD]) is found to be protective for tyrosinemia." (PMID 26755558, 2016).
tyrosinemia (continued). "The diagnosis of type I tyrosinemia is confirmed by measurement of FAH enzyme activity in cultured fibroblasts (or on liver tissue) and/or detection of disease-causing mutations in the FAH gene." (PMID 20003495, 2009). "This approach was inspired by the metabolic disorder type I hereditary tyrosinemia, in which the absence of fumarylacetoacetate hydrolase leads to the accumulation of the hepatotoxic metabolite fumarylacetoacetate and ultimately to liver failure." (PMID 33450224, 2021). "To investigate the effect of the inhibitors (G2-compounds and G1.30.B10) in the tyrosinemia catabolism, we employed CRISPR/Cas9 technology to transform HEK293 cells into human cellular models of HT1 by replacing the endogenous FAH WT by means of the generation of the carrying G337S." (PMID 33670179, 2021).
liver failure (20 papers, 2011 to 2025). A liver disease characterized by the liver losing or has lost all of its function. "Results showed that fumarylacetoacetate hydrolase (Fah) deficiency led to liver failure, and double knock out of Rag2 and the gamma chain of the IL-2 receptor resulted in sufficient human liver cell repopulation in mice." (PMID 29511142, 2018). "Using fumarylacetoacetate hydrolase–deficient (Fah−/−) mice as a liver-failure model, we confirmed that BMDHs were generated by fusion of BM-derived CD11b+F4/80+myelomonocytes with resident Fah−/− hepatocytes." (PMID 26345133, 2015). "Aberrations in the FAH gene cause HT1, resulting in reduced activity and subsequently leading to hepatic failure, cirrhosis, renal dysfunction and HCC." (PMID 33218190, 2020). "Due to a genetic defect in the enzyme fumarylacetoacetate hydrolase (FAH), several toxic products accumulate, causing liver failure, renal tubulopathy, rickets, cardiomyopathy, porphyria like syndrome, and hepatocellular carcinoma." (PMID 28949985, 2017). "Upon transplantation of clonal lines to a Fah−/−Il2rg−/− rat model of liver failure, the rat liver stem cells engrafted into the host liver where they differentiated into areas with FAH and Albumin positive hepatocytes." (PMID 26915950, 2016). "NTBC-treated FAH −/− knock-out mice developed liver failure or died after complete withdrawal of NTBC." (PMID 25081276, 2014). "All mice derived from FAHgc-iPS #7.7 appeared very weak after NTBC withdrawal and presented characteristics of liver failure with very few FAH-positive liver cells." (PMID 21765802, 2011). "Fumarylacetoacetate hydrolase-deficient (Fah−/−) mice defective in tyrosine metabolism require a supply of 2-(2-nitro-4-trifluoromethylbenzoyl)-1, 3-cyclohexanedione (NTBC) for survival, otherwise mice will die of liver failure." (PMID 29796307, 2018). "These bipotent epithelial liver organoids could be differentiated into mature and functional hepatocytes in vitro and could rescue liver failure in the fumarylacetoacetate hydrolase (Fah−/−) mutant mouse, a model for tyrosinemia type I liver disease, after transplantation." (PMID 31921856, 2019).